DUSP5 (dual specificity phosphatase 5)
Diseases named in the same sentence as DUSP5 in open-access papers (continued):
Sharing a sentence is not in itself a finding about the gene and the disease.
pterygium (2 papers, 2020 to 2022). A wedge-shaped fibrovascular lesion arising from the bulbar conjunctiva and extending to the cornea. "Both expressions of miR-199a-3p and miR-199a-5p were significantly increased in pterygium (p < 0.0001), while expressions of DUSP5 (p = 0.0124) and MAP3K11 (p = 0.0005) were significantly decreased in pterygium." (PMID 32867783, 2020). "Our present research presented that TGF-β and EGF activated the miR-199a-3p/5p-DUSP5/MAP3K11-MAPK axes in the EMT process of pterygium." (PMID 32867783, 2020). "The validated results in tissues showed that, compared with control conjunctival tissues, miR-199a-3p/5p were more overexpressed in pterygium, while DUSP5/MAP3K11 were lower expressed." (PMID 32867783, 2020). "Accordingly, our study found that both DUSP5 and MAP3K11 implicated in MAPK signalling pathway, might be a potential therapeutic agent targeted specifically to reverse EMT in pterygium." (PMID 32867783, 2020). "Moreover, hsa-miR-199a-3p targets DUSP5 in our network have been confirmed in pterygium." (PMID 36187094, 2022). "Downregulated protein expressions of DUSP5 and MAP3K11 in pterygium tissues were verified by western blot." (PMID 32867783, 2020). "MiR-199a-3p-DUSP5 and miR-199a-5p-MAP3K11 axes regulated EMT in pterygium were characterized in our study." (PMID 32867783, 2020). "So, we speculated that miR-199a-3p and miR-199a-5p might target DUSP5 and MAP3K11 to function in EMT of pterygium." (PMID 32867783, 2020). "TGF-β and EGF induce EMT of HCEs through miR-199a-3p/5p-DUSP5/MAP3K11 axes, which explains the pathogenesis of EMT in pterygium and may provide new targets for pterygium prevention and therapy." (PMID 32867783, 2020). "Furthermore, it presented that miR-199a-3p and miR-199a-5p participated in the process of EMT induced by TGF-β and EGF, by targeting DUSP5 and MAP3K11 in pterygium." (PMID 32867783, 2020). "That is to say, TGF-β and EGF affected the expression of DUSP5 and MAP3K11 through regulations on expressions of miR-199a-3p and miR-199a-5p, so as to take part in the MAPK signalling pathway, further to promote the EMT of HCEs, and participate in the initiation and development of pterygium." (PMID 32867783, 2020).
rheumatoid arthritis (2 papers, 2020 to 2021). A chronic, systemic autoimmune disorder characterized by inflammation in the synovial membranes and articular surfaces. "Some studies reported that DUSP1, DUSP2, and DUSP5 are involved in osteoclast-related diseases, such as osteoporosis and rheumatoid arthritis, but the role of DUSP6 has not been studied." (PMID 34475393, 2021).
skin papilloma (2 papers, 2021 to 2022). A benign papillary neoplastic growth on the skin composed of epithelial cells and a fibrous stalk. "Recent studies using knockout mice and cells derived from them have confirmed a key role for DUSP5 in the regulation of nuclear ERK activity and the suppression of mutant HRASQ61L-driven DMBA/TPA-induced skin papillomas, confirming a tumour suppressor function for this phosphatase." (PMID 35418690, 2022).
Stroke (2 papers, 2020). Sudden impairment of blood flow to a part of the brain due to occlusion or rupture of an artery to the brain. "The results from this manuscript demonstrate, for the first time, that DUSP5 contributes to the regulation of the passive mechanical properties of cerebral and renal arterioles and provide new insights into role of DUSP5 in vascular function, cancer, stroke, and other cardiovascular diseases." (PMID 31960618, 2020). "Importantly, in contrast to other genetic models of enhanced cardiomyocyte proliferative growth, the morphological changes observed here during development in Dusp5–/– mice do not impact negatively on stroke volume, body weight or survival." (PMID 33318551, 2020).
teratoma (2 papers, 2022 to 2024). A non-seminomatous germ cell tumor characterized by the presence of various tissues which correspond to the different germinal layers (endoderm, mesoderm, and ectoderm). "Another interesting finding in this study is the mutation p.Ala220Met of the DUSP5 gene in all teratomas." (PMID 36289533, 2022). "Moreover, novel mutations in DUSP5 and PHLDA1 genes found on WES may help to explain the characteristics of teratoma." (PMID 36289533, 2022). "Moreover, novel mutations in DUSP5 and PHLDA1 genes found on whole-exome sequencing may help to explain the characteristics of teratomas." (PMID 36289533, 2022).
thyroid tumor (2 papers, 2017 to 2023). A benign or malignant neoplasm affecting the thyroid gland. "We report here for the first time the positive role of DUSP5 on in vitro cell migration and invasion in two BRAFV600E thyroid tumor cell lines, as indicated by the decreased capacity of migration and invasion after DUSP5 invalidation in the 8505c and BCPAP cell lines." (PMID 28910386, 2017). "DUSP5 and DUSP6 expression levels were higher in human thyroid tumors than in the tumor-free tissue and controls." (PMID 37964961, 2023).
cardiomyopathy (1 paper, 2020). A disease of the heart muscle or myocardium proper. "DUSP4 and DUSP5 can be transcriptionally induced by ERK1/2, which suggests the possibility of ERK1/2 pathway activation in LMNA cardiomyopathy progression." (PMID 32313136, 2020).
Cognitive impairment (1 paper, 2023). Abnormal cognition is characterized by deficits in thinking, reasoning, or remembering. "To conclude, our findings provide evidence that targeting DUSP5 could be a promising approach for ameliorating cerebral hypoperfusion and cognitive impairment in AD/ADRD." (PMID 37588944, 2023).
cystic teratomas of the ovary (1 paper, 2022). "Among the prevalent mutated genes, 7 with the same variant in exons with changes in protein coding are important for the development of mature cystic teratomas of the ovary: PTGFRN, DUSP5, MPP2, PHLDA1, PRR21, GOLGA6L2, and KRTAP4-2." (PMID 36289533, 2022).
Kashin-Beck disease (1 paper, 2023). Disabling osteochondrodysplasia with osteosclerosis, cone-shaped metaphysis, and shortening of the diaphysis. "Hsa_circ_0020014 (circ_0020014), derived from the dual-specificity phosphatase 5 (DUSP5) gene, has been revealed as a potential biomarker for differential diagnosis of OA and Kashin-Beck disease." (PMID 37980493, 2023).
liver cirrhosis (1 paper, 2019). "Our analysis of human GEO database and the experiments using animal models found that the hepatic expression of DUSP5 increased in patients with liver cirrhosis, and in mice with liver fibrosis at both transcript and protein levels." (PMID 31491992, 2019).
liver diseases (1 paper, 2019). "Of note, DUSP5 expression was profoundly enhanced in acutely injured liver of mice exposed to liver toxicants, implying the possible detrimental roles of DUSP5 in early pathogenic events during liver disease progression." (PMID 31491992, 2019). "Taken together with the induction of DUSP5 expression in liver diseases, it seems that DUSP5 may contribute to the pathogenesis of ER stress-associated liver disease progression." (PMID 31491992, 2019). "An important finding of the present study is the identification of DUSP5 as a phosphatase changed in liver diseases and a novel potential marker of liver injury." (PMID 31491992, 2019). "Analysis of Gene Expression Omnibus (GEO) database showed that hepatic DUSP5 levels increased in the patients with liver fibrosis, which was verified in mouse models of liver diseases with ER stress." (PMID 31491992, 2019). "Thus, the precise mechanisms and roles of DUSP5 in cell death and liver disease progression require further examinations and in vivo validation in future studies." (PMID 31491992, 2019).
peripheral artery disease (1 paper, 2020). "Several genes were previously shown upregulated in circulating leukocytes in patients with peripheral artery disease (FCAR, FFAR2, DUSP5, PLAUR)." (PMID 31875423, 2020).
pulmonary fibrosis (1 paper, 2020). Chronic progressive interstitial lung disorder characterized by the replacement of the lung tissue by connective tissue, leading to progressive dyspnea, respiratory failure, or right heart failure. "Some studies have revealed that DUSP5 has an anti-inflammatory function and participates in the pathogenesis of several diseases, including pulmonary fibrosis, autoimmune arthritis, cardiovascular disease, and cancer." (PMID 33361528, 2020).
rectal cancer (1 paper, 2023). A primary or metastatic malignant neoplasm that affects the rectum. "DUSP5 expression is significantly downregulated in patients with gastric or rectal cancer, and endoplasmic reticulum stress can affect the expression of DUSP5 via the PERK-CHOP pathway." (PMID 37766214, 2023).
T-cell leukemia (1 paper, 2015). A malignant disease of the T-lymphocytes in the bone marrow, thymus, and/or blood. "As mechanism of action, miR181 targets PTPN, DUSP5, and DUSP6, resulting in PI3K/AKT activation and tumorigenesis in murine T-cell leukemia." (PMID 26436088, 2015).
thyroid (1 paper, 2017). "DUSP5 and DUSP6 are specifically induced by the MEK-ERK pathway in the three PTC oncogenes inducible thyroid cell lines." (PMID 28910386, 2017).
type 2 diabetes (1 paper, 2021). "Rosiglitazone induced an increase in both of DUSP1 and DUSP5; while metformin, a first-line treatment for type 2 diabetes, enhanced DUSP5 expression." (PMID 33995033, 2021).
tumor (60 papers, 2011 to 2026). "Differential expression of key metastasis-associated genes (CDH1, JUNB, and DUSP5) confirmed the scaffold’s ability to recapitulate important molecular features of the tumor microenvironment." (PMID 40558895, 2025). "And gain-of-function and loss-of-function revealed that DUSP5 functionedas a tumor suppressor in HCC cells." (PMID 29312625, 2017). "Indeed, compared with controls, tumours from DUSP5 KO mice showed increased phosphorylation of nuclear ERK1/2 that was associated with the support of tumour growth." (PMID 40943262, 2025). "Additionally, our clusters based on the DUSP5-originated genomic model exhibited distinct immune microenvironments, tumor mutational burden (TMB), and prognostic characteristics in LUAD." (PMID 38872157, 2024). "In addition, the DUSP5-derived genomic model revealed the two clusters with distinguishable immune features and tumor mutational burden (TMB)." (PMID 38872157, 2024). "In contrast, loss of BAF53A blocks tumor growth and induces DUSP5 expression in vivo." (PMID 36526622, 2022). "In a carcinogen-induced model, DUSP5 knockout increased tumor burden, effects reversed by ERK1/2 inhibition." (PMID 41956999, 2026). "Another IHC study showed that DUSP5 is also downregulated in CRC specimens compared to normal tumour-surrounding tissue." (PMID 40943262, 2025). "The tumor-suppressive effect of DUSP5 is attributed to its role in MAPK pathway inhibition, which causes cell cycle arrest and apoptosis." (PMID 38926346, 2024). "Conversely, upregulation of DUSP5 suppresses tumor growth, inhibiting proliferation and invasion, indicating its potential as a therapeutic target." (PMID 39628997, 2024). "GHRL, KLF4, and DUSP5 expression levels were relatively lower in tumor tissues, whereas DSP, PERP, and MMP9 were highly expressed in tumor tissues." (PMID 38273348, 2024). "DUSP5 expression was significantly elevated in tumor tissue samples than in normal lung tissue samples based on the TCGA-LUAD dataset." (PMID 38872157, 2024). "DUSP5 knockdown attenuated the gefitinib resistance in these cells, as evidenced by reduced tumor volume and tumor weight." (PMID 38872157, 2024). "DUSP5, which in varying contexts can act either as a tumor suppressor or promoter, is seen to be highly expressed specifically in the upper left tumor region." (PMID 37426750, 2023). "In conclusion, our results confirm a tumour suppressor role for both DUSP5 and DUSP6 in a clinically relevant model of mutant KRAS-driven oncogenesis." (PMID 35418690, 2022). "TCGA analysis showed that DUSP5 expression was lower in tumor tissues than in matched normal tissues." (PMID 36526622, 2022). "In recent years, many studies have demonstrated that DUSP5 is widely involved in tumor progression and metastasis." (PMID 31821724, 2020). "IHC staining of TMAs showed clear and distinguishable cytoplasm staining for DUSP5 in tumor tissues, and DUSP5 expression was significantly lower in FTC tissues compared to PTC tissues (P < 0.05)." (PMID 31821724, 2020). "According to previous reports, G9a activity increases, causing an increase in global histone methylation, and further cause transcriptional repression of different tumor suppressors, including CDH1, DUSP5, SPRY4, and RUNX3." (PMID 32015216, 2020). "SR9243 also upregulated or downregulated genes associated with tumour proliferation, apoptosis, angiogenesis, invasion and migration, such as ANGPTL4, PDGFR, DUSP5, MMP7, FOXQ1 and MXD1 26–31." (PMID 31138790, 2019). "Some reports attribute tumor suppressor activities to DUSP5, and a dual role for this MKP in carcinogenesis, depending on the tissue and cellular context, has been proposed." (PMID 30866462, 2019). "To determine the tumour suppressive effects of DUSP5 in the intestinal epithelium in vivo, we crossed Vil1-DUSP5Tg with ApcMin/+ mice." (PMID 29379130, 2018). "DUSP5 is a well‐established tumor suppressor exerting its anticancer effects through inactivating MAP signaling pathway." (PMID 29341479, 2018).
tumor (continued). "The relative level of DUSP5 expression in the tumor tissue samples was significantly lower than that in corresponding histologically normal tissues (p<0.01)." (PMID 29312625, 2017). "To further elucidate the correlations between HOXA11-AS and DUSP5 in HCC, we measured the level of DUSP5 in 66 HCC tumor tissue samples." (PMID 29312625, 2017). "In mouse xenografts, overexpression of DUSP5 reduced tumor growth and metastasis." (PMID 41956999, 2026). "Suppression of DUSP5 impeded tumor metastasis and EGFR-TKI resistance in LUAD cells." (PMID 38872157, 2024). "Our data suggest that loss of either DUSP5 or DUSP6, as observed in certain human tumours, including the pancreas, could promote carcinogenesis." (PMID 35418690, 2022). "Moreover, up-regulation of Dusp5 (a tumor suppressor) is able to negatively regulate the MAPK signaling pathway." (PMID 32140303, 2020). "Finally, previous work has shown that DUSP5 exhibits tumour suppressive activity in a mouse model of carcinogen-induced skin tumorigenesis." (PMID 29379130, 2018). "However, it is conceivable that other in vivo substrates of DUSP5 are involved in its role as a tumor suppressor, since at least 10 different DUSP proteins have the ability to dephosphorylate ERKs12." (PMID 29229953, 2017). "DUSP5 is a tumor suppressor and has been reported to be down-regulated in certain cancers." (PMID 29312625, 2017). "Recent reports have proposed that DUSP5 may act as a tumor suppressor by regulating ERK activity in several types of cancer." (PMID 29229953, 2017). "While these limited studies indicate that DUSP5 might act as a tumour suppressor, they rely on correlation between expression level and clinical outcome coupled with over expression of DUSP5 in vitro." (PMID 26791049, 2016). "It will be very interesting to determine if DUSP5 plays a wider role as a tumour suppressor in more clinically relevant mouse models of Hras or Braf-driven cancers such as pancreas, lung or intestinal tumours and to determine the extent to which it is deregulated in a wider range of human cancers." (PMID 26791049, 2016). "Overall this work demonstrates that DUSP5 has an essential non-redundant function in regulating both the activity and localisation of nuclear ERK signalling and that DUSP5 also acts as a tumour suppressor to limit the oncogenic potential of mutant HrasQ61L in this cancer model." (PMID 26791049, 2016). "However, a recent study using a combination of genetic and biochemical studies has now provided the first evidence of a bona fide tumour suppressor function for DUSP5." (PMID 26791049, 2016). "Therefore, the benefit of inhibiting a “putative tumor suppressor,” such as DUSP5, and in turn accelerating the disease etiology to a phase where the disease regresses is counterintuitive." (PMID 26286528, 2015). "The ERK pathway plays an important role in HL pathogenesis and inhibition of the negative regulator DUSP5 might be important for proliferation and survival of tumor cells as indicated by the low expression of DUSP5 in the majority of tumor cells." (PMID 24651368, 2014). "Additionally, corin treatment with or without PLX4032 led to increased expression of H3K4Me2, H3K27Ac, DUSP1, and DUSP5, as well as increased expression of markers of apoptosis and tumor hypoxia in BRAFi-R tumors, with associated decreases in the expression of both MITF and AXL." (PMID 38300709, 2024). "Given the evidence that the RAS/ERK signalling pathway is a critical mediator of both tumour initiation and maintenance in the pancreas future work should also concentrate on the identification of the critical ERK-dependent targets that are affected by loss of either DUSP5 or DUSP6." (PMID 35418690, 2022). "Thus, DUSP5 may be a novel addition to the panel of genes preferentially methylated in this tumour subset." (PMID 29379130, 2018).